CRP (C-reactive protein)
Diseases named in the same sentence as CRP in open-access papers (continued):
Sharing a sentence is not in itself a finding about the gene and the disease.
eosinophilic bronchiectasis (1 paper, 2024). A bronchiectasis inflammatory endotype characterized by elevated blood eosinophils (≥300 cells/μL) or sputum eosinophils (≥3%), associated with type 2 (Th2) inflammation, elevated fractional exhaled nitric oxide (FeNO), and IL-5/IL-13 signaling. "The median white blood cell (WBC), lymphocyte, platelet (PLT) and C-reactive protein (CRP) levels in eosinophilic bronchiectasis were significantly increased." (PMID 38408986, 2024). "In our cohort, eosinophilic bronchiectasis presented with increased level of WBC, lymphocyte count, PLT, and C-reactive protein (CRP) and the number of PLT was positively associated with the level of BEC, suggesting the presence of elevated inflammation in eosinophilic subtype." (PMID 38408986, 2024).
Erdheim-Chester disease (1 paper, 2018). "Elevated CRP level was more frequent with Erdheim-Chester disease than idiopathic pachymeningitis (78% vs 42%, P = .012)." (PMID 30045263, 2018).
extrapulmonary tuberculosis (1 paper, 2024). A tuberculosis that occurs at body sites other than the lung. "We aimed to assess the plasma levels of ferritin, C-reactive protein (CRP), and adenosine deaminase (ADA) at baseline and their utility as biomarkers to monitor response to treatment in extrapulmonary tuberculosis (EPTB) patients." (PMID 39623309, 2024).
Fanconi’s syndrome (1 paper, 2013). "The current research was initially driven by the report on the decreased CRP level, an important regular of cystatin C level, and evidence of abnormalities of renal tubular function in HNF1A-MODY subjects and a Fanconi’s syndrome in an animal model." (PMID 22350134, 2013).
female infertility (1 paper, 2026). Diminished or absent ability of a female to achieve conception. "Exploratory mediation analysis highlighted that inflammation (via C-reactive protein) and hormonal pathways (via estradiol) mediated numerous associations, such as the C-reactive protein-mediated protective effect of MVPA on female infertility." (PMID 42116317, 2026).
fertility disorders (1 paper, 2008). "CRP levels are considered marker for inflammation and its association with pDCs in women with fertility disorders suggests that pDCs are involved either in induction or in maintenance of inflammatory responses." (PMID 18828896, 2008). "Further, median CRP levels were found to be significantly higher in women with fertility disorders and showed significant correlation with pDCs." (PMID 18828896, 2008). "Median CRP levels were found to be significantly higher in women with fertility disorders and showed significant correlation with pDCs/cervical sample (r = 0.63, P < 0.05)." (PMID 18828896, 2008). "pDCs correlated significantly with C-reactive protein levels, IL-6 and IFN-gamma levels in women with fertility disorders." (PMID 18828896, 2008). "C-reactive protein (CRP) levels and sex hormone levels in the sera of women with and without fertility disorders were also studied to understand the basic question in chlamydial pathogenesis as to why some women clear infection while others develop sequelae." (PMID 18828896, 2008).
forearm fracture (1 paper, 2021). "DAMPs, inflammatory cytokines and CRP concentration results in plasma of children with distal forearm fracture and in the control group." (PMID 34956079, 2021).
frontotemporal lobar degeneration (1 paper, 2019). "Here, we aimed to analyze the lipoprotein profile and inflammatory indicators, the high-sensitivity C-reactive peptide (hs-CRP) and glycoprotein acetyls (GlycA), in sporadic and C9orf72 repeat expansion-associated frontotemporal lobar degeneration (FTLD) patients." (PMID 31561355, 2019).
Gastrointestinal dysmotility (1 paper, 2020). Abnormal intestinal contractions, such as spasms and intestinal paralysis, related to the loss of the ability of the gut to coordinate muscular activity because of endogenous or exogenous causes. "DKT improve gastrointestinal dysmotility and reduce serum CRP levels in patients with grade B liver damage after hepatectomy." (PMID 32766269, 2020).
genital herpes (1 paper, 2017). Herpes simplex infection of the genitals, most commonly caused by the herpes simplex-2 virus. "Patient #7 suffered of genital herpes at age 24 with strong local symptoms but no signs of systemic infection as in fever or elevated CRP levels." (PMID 28861081, 2017).
geographic atrophy (1 paper, 2018). "However, in advanced dry AMD eyes with geographic atrophy (GA), CRP immunoreactivity in the non-atrophic area was similar to that of age-matched controls, with CRP levels significantly reduced within the atrophic lesions." (PMID 29599782, 2018).
Gingival bleeding (1 paper, 2021). Hemorrhage affecting the gingiva. "To better understand our observed association between 25(OH)D and acute gingival bleeding in our cohort of postmenopausal women, we examined associations between plasma 25(OH)D concentrations and both salivary C-reactive protein (CRP) and serum CRP concentrations, acute measures of inflammation." (PMID 33807159, 2021).
glucocorticoid resistance (1 paper, 2019). "Irrespective of glucocorticoid resistance levels, patient levels of CRP (d = 0.23; 95% CI, −0.01 to 0.46), IFN-γ (d = 0.22; 95% CI, −0.02 to 0.47), IL-1β (d = 0.18; 95% CI, −0.24 to 0.61), and IL-2 (d = −0.12; 95% CI, −1.04 to 0.80) were all not significantly different from control." (PMID 31316402, 2019).
gram-negative bacterial meningitis (1 paper, 2022). "Studies have shown that CSF CRP level is significantly higher in gram-negative bacterial meningitis than in gram-positive meningitis." (PMID 35974935, 2022).
growth failure (1 paper, 2019). "The association of CKD5 and dialysis with growth failure was not explained by variation of hemoglobin, serum bicarbonate, PTH, phosphorus or CRP (model 2)." (PMID 31334210, 2019).
haemochromatosis (1 paper, 2024). "One participant’s 12-week hs-CRP result and all 3 ferritin results were excluded from analysis due to illness and a subsequent diagnosis of haemochromatosis." (PMID 38547224, 2024).
hemangioma (1 paper, 2025). A benign vascular lesion characterized by the formation of capillary-sized or cavernous vascular channels. "SAA and CRP, acute-phase inflammatory markers, emerged as significant contributors, suggesting a pivotal role of immune responses in hemangioma development." (PMID 41255770, 2025).
hemophilia (1 paper, 2020). Hemophilia is a genetic disorder characterized by spontaneous hemorrhage or prolonged bleeding due to factor VIII or IX deficiency. "This study has demonstrated that serum CRP and MIF levels increases in acute bleeding period regardless of the presence of previous joint damage in children with severe hemophilia and that CRP elevation may be a useful and rapid marker for acute bleeding in severe hemophilia A patients." (PMID 33023246, 2020).
hemorrhagic cystitis (1 paper, 2022). Inflammation of the bladder resulting in bloody urine. "The present study provided evidence that IPG exerts anti-inflammatory and antioxidant activities which modulate the hallmarks underlying hemorrhagic cystitis, as it reduced the levels of TNF-α, IL-1β, MDA, and C-reactive protein, as well as increasing SOD levels and reducing edema and hemorrhage." (PMID 35625456, 2022).
hemorrhagic fever with renal syndrome (1 paper, 2022). A viral infectious disease that is a hemorrhagic fever, located_in kidney, has_material_basis_in Hantaan virus, has_material_basis_in Dobrava-Belgrade virus, has_material_basis_in Seoul virus, or has_material_basis_in Puumala virus, which are carried and transmitted_by rodents. "This study aimed to analyze the clinical significance of serum ferritin, procalcitonin (PCT), and C-reactive protein (CRP) in patients with hemorrhagic fever with renal syndrome (HFRS)." (PMID 35677912, 2022).
hemosiderosis (1 paper, 2025). Accumulation of iron in internal organs. "On May 31, 2023, a dermatology consultation was requested, and the immune-related examinations showed weakly positive antinuclear antibody (ANA), IgG 6.620 g/L, hemosiderosis (ESR) 65.0 mm/h, and C-reactive protein (CRP) 99.500 mg/L." (PMID 41019088, 2025).
hemostatic disorders (1 paper, 2021). "The hemostatic disorders are strongly related to the systemic inflammation that not only triggers the blood clotting system, but also interferes with the hemostatic chronometric tests via direct anticoagulant effects of C-reactive protein (CRP) and antiphospholipid antibodies." (PMID 34381066, 2021).
Hepatic hemangioma (1 paper, 2025). A congenital vascular malformation in the liver composed of masses of blood vessels that are atypical or irregular in arrangement and size. "Furthermore, the white blood cell count, CRP, C3, C4, CH50, and ESR improved, suggesting that the unknown fever might have been caused by the necrotic area of the hepatic hemangioma." (PMID 40404957, 2025).
HOMA-IR (1 paper, 2020). The HOMA-IR measurement employs the homeostatic model assessment (HOMA) to quantify insulin resistance. "Overall, there were significant differences (p < 0.05) between the LGI and control groups with respect to weight, glycated hemoglobin, insulin, Homa-IR, triglycerides, hs-CRP and ApoB." (PMID 32867226, 2020).
hydatidiform mole (1 paper, 2019). A gestational trophoblastic disorder characterized by marked enlargement of the chorionic villi, hyperplasia of the villous trophoblastic cells and hydropic changes. "In addition, we did not compare RDW values with other well‐known inflammatory parameters such as CRP, erythrocyte sedimentation rate (ESR), etc These indicators may help elucidate the mechanism by which RDW is elevated in patients with invasive hydatidiform mole." (PMID 30883924, 2019).
hyperemesis gravidarum (1 paper, 2016). Severe, intractable vomiting during pregnancy (usually the first trimester) accompanied by dehydration, weight loss, and electrolyte imbalances. "The high sensitivity-C reactive protein (hs-CRP) is an inflammatory marker and vitamin D is an immune modulator that might play a critical role in the pathogenesis of hyperemesis gravidarum." (PMID 28913106, 2016).
hyperkyphosis (1 paper, 2023). "Furthermore, elevated C-Reactive Protein (CRP), disease duration, and hyperkyphosis have also been linked to an increased risk of VFs5." (PMID 37758825, 2023).
Hypermagnesemia (1 paper, 2025). An abnormally increased magnesium concentration in the blood. "The hypermagnesemia group had the highest mean values for serum magnesium (3.0 ± 1.7 mg/dL), CRP (129.7 ± 84.6 mg/L), NLR (15.2 ± 10.8), PLR (328.7 ± 205.9), SII (4324 ± 3211), and MII (564.3 ± 337.4 × 103)." (PMID 41189164, 2025).
hypospadias (1 paper, 2021). Hypospadias is the displacement of the urethral meatus on the ventrum of the penis. "The results showed that the length of the urethral defect (P = 0.006), the resource of urethral skin flap (P = 0.004), the surgical procedure (P = 0.009), and CRP (P < 0.001) were the risk factors affecting the success rate of hypospadias." (PMID 34589449, 2021). "This study retrospectively analyzed the clinical and follow-up data of 106 children with hypospadias and found that the urethral skin flap and CRP, as independent risk factors, had a high predictive value for postoperative complications." (PMID 34589449, 2021). "The length of the urethral defect and the CRP level were the independent risk factors of the prognosis of hypospadias patients." (PMID 34589449, 2021). "Urethral material and postoperative CRP value are independent risk factors for the prognosis of patients with hypospadias." (PMID 34589449, 2021). "In this study, the CRP value on the first postoperative day was associated with the occurrence of a urethral fistula (P < 0.001), and both urethral skin flap and CRP were independent risk factors affecting the success rate of hypospadias surgery." (PMID 34589449, 2021). "We hypothesized that CRP is associated with surgical outcomes in patients with hypospadias." (PMID 34589449, 2021). "The aim of this study was to confirm the relationship between postoperative complications of hypospadias and CRP." (PMID 34589449, 2021). "In conclusion, the length of the urethral defect, urethral material, surgical method, and CRP are related to the prognosis of patients with hypospadias." (PMID 34589449, 2021). "Relationship between CRP and clinical characteristics in hypospadias." (PMID 34589449, 2021). "The sensitivity and the specificity of CRP for hypospadias were 100 and 76.2%, respectively." (PMID 34589449, 2021).
idiopathic scoliosis (1 paper, 2025). A scoliosis with no known cause. "In this retrospective study, we analyzed postoperative serum CRP concentrations in patients undergoing surgical correction of idiopathic (IS) and non-idiopathic scoliosis (N-IS) to evaluate its utility as an early marker of surgical site infection (SSI)." (PMID 41226908, 2025). "Therefore, the aim of this study was to evaluate the diagnostic value of postoperative serum C-reactive protein (CRP) levels for the early identification of surgical site infections in patients undergoing surgery for idiopathic and non-idiopathic scoliosis." (PMID 41226908, 2025).
ileitis (1 paper, 2023). "Finally, despite our best efforts, other potentially informative clinical data (presence of backwash ileitis at the time of colectomy, erythrocyte sedimentation rate, C-reactive protein, fecal calprotectin, etc.)could not be included due to a high degree of missingness." (PMID 37663924, 2023).
ileocolitis (1 paper, 2024). Ileocolitis or ileal Crohn's is the most common type of Crohn's disease. "Both had experienced moderate flare-ups of ileocolitis (HBI, 8 and 9 points; respectively) with CRP > 2.5 mg/L and FC > 600 μg/g." (PMID 38398390, 2024).
immunotoxicity (1 paper, 2018). "Results from the sparse PLS models selecting both exposures and proteins suggest a swimming-induced immunotoxicity through decreased level of IL-8, VEGF, CCL22, CCL11, CRP and CXCL10, and increased levels of IL-1ra, which antagonises the proinflammatory IL-1." (PMID 29563153, 2018).
infantile hemangioma (1 paper, 2025). "Patient 1: The model predicted a high probability (0.82) of developing infantile hemangioma, primarily driven by elevated CRP and SAA levels, preterm birth, and multiple pregnancy, indicating a high-risk profile." (PMID 41255770, 2025). "The overlap of top-ranked features across all models consistently identified multiple pregnancy, preterm birth, low birth weight, and elevated VEGF, CRP, and SAA levels as the strongest predictors of infantile hemangioma." (PMID 41255770, 2025).
infectious keratitis (1 paper, 2024). "In the physiological aspect, the existence of both DM and chronic ischemic heart disease is associated with a high level of c-reactive protein, and the c-reactive protein expression would also elevate in those with infectious keratitis." (PMID 39335693, 2024).
infectious thyroiditis (1 paper, 2024). "Erythrocyte sedimentation rate (ESR) and C-reactive protein (CRP) are significantly elevated in infectious thyroiditis." (PMID 39435250, 2024).
Korsakoff syndrome (1 paper, 2022). "By contrast, the results of the present work suggested a trend toward higher CRP levels in patients with Korsakoff syndrome." (PMID 36358351, 2022). "CRP levels tended to be higher in patients with Korsakoff syndrome than in the control group and in AD patients." (PMID 36358351, 2022). "CRP levels showed a trend toward statistical significance, and significant differences were detected when we conducted pairwise comparisons between patients affected by Korsakoff syndrome and the control group, and between patients affected by Korsakoff syndrome and AD patients." (PMID 36358351, 2022). "More specifically, patients affected by Korsakoff syndrome displayed higher CRP levels compared to non-demented, depressed patients, as well as AD patients." (PMID 36358351, 2022).
laryngeal diseases (1 paper, 2024). "Nasal disease also resulted in a significant increase in CRP levels compared to pharyngeal and laryngeal diseases." (PMID 38250933, 2024).
laryngeal squamous cell carcinoma (1 paper, 2024). A squamous cell carcinoma that arises from the larynx. "The multivariate regression analysis identifies CRP (p-value 0.008), T stage (p-value 0.001), and neck node involvement (p-value 0.047) as significant predictors of PD-L1 expression (CPS) in patients with laryngeal squamous cell carcinoma." (PMID 39069571, 2024).
laryngitis (1 paper, 2024). An acute or chronic, bacterial or viral inflammatory process affecting the larynx. "In our study, it was observed that even 26.7% of laryngitis cases had CBC and CRP tests performed, despite diagnosis traditionally being reliant solely on clinical signs." (PMID 38786268, 2024).
Lassa fever (1 paper, 2025). A viral hemorrhagic fever that is caused by the Lassa virus, which is transmitted by contact with infected rodents; it is characterized by fever, headache, malaise, myalgia, and hearing loss. "With enhanced laboratory capabilities at our institution, the Institute of Lassa Fever Research and Control at Irrua Specialist Teaching Hospital, we conducted a prospective cross-sectional study to assess CRP levels across the clinical spectrum of LF in southern Nigeria." (PMID 39877415, 2025).
Lassa virus infection (1 paper, 2025). "CRP levels in patients suspected of having Lassa virus infection may serve as a potential baseline marker to guide management decision-making whether to treat or not to treat." (PMID 39877415, 2025).
liver neoplasm (1 paper, 2024). Tumors or cancers of the LIVER. "Lastly, the majority of the RE group had normal CRP values, with only two dogs having abnormal values due to hepatic encephalopathy secondary to liver neoplasm or a concomitant infectious disease." (PMID 39330787, 2024).
loiasis (1 paper, 2025). Loiasis is a form of filariasis (see this term), caused by the parasitic worm Loa loa, endemic to the forest and savannah regions of Central and Western Africa. "Besides this, substantial elevation of IgE levels with at the same time unremarkable inflammatory markers (such as C-reactive protein) are common in loiasis before the start of treatment." (PMID 40397272, 2025).
lung neoplasm (1 paper, 2021). A benign or malignant, primary or metastatic neoplasm involving the lungs. "There was also a significant positive correlation between acute-phase protein concentrations, SAA1, and CRP in patients with all types of lung neoplasm except adenocarcinoma, with correlation coefficients of 0.44 in SqCC, 0.72 in other NSCLC, and 0.80 in other lung neoplasms." (PMID 34439874, 2021).
lymphangiectasia (1 paper, 2022). "However, given that the CRP had normalized in this dog and that the other dogs with lymphangiectasia or lacteal dilation on intestinal histopathology still had increased concentrations of cholesterol following the diet suggests that there might be another reason for this dog’s decrease." (PMID 35739930, 2022).
Lymphatic Metastasis (1 paper, 2025). Transfer of a neoplasm from its primary site to lymph nodes or to distant parts of the body by way of the lymphatic system. "Additionally, this study identified that monocyte-to-lymphocyte ratio (MLR), pan-immune inflammatory value (PIV), and CRP levels were significantly higher in patients with lymphatic metastasis." (PMID 40429363, 2025).
lymphoid neoplasm (1 paper, 2019). A neoplasm composed of a lymphocytic cell population which is usually malignant (clonal) by molecular genetic and/or immunophenotypic analysis. "Moreover, in the lymphoid neoplasm group, the GM3(d18:1-16:0) levels were significantly and positively correlated with the levels of C-reactive protein, soluble interleukin-2 receptor, and lactate dehydrogenase." (PMID 31004109, 2019).